SLC38A11 (solute carrier family 38 member 11)
Description:
Putative sodium-dependent amino acid/proton antiporter.
Synonyms: AVT2; FLJ39822
Tractability: Antibody: UniProt predicts a signal peptide or a membrane-spanning region.
Gene: Protein-coding gene on chromosome 2 (164,894,354 to 164,955,525, reverse strand). Ensembl gene ENSG00000169507.
Subcellular location: Membrane
Gene Ontology:
Molecular function: protein binding; L-amino acid transmembrane transporter activity
Biological process: amino acid transmembrane transport; L-alpha-amino acid transmembrane transport
Cellular component: membrane
Genetic constraint (gnomAD): Loss-of-function variants: 31 observed, 26.56 expected, observed/expected ratio (o/e) 1.17, 90% interval 0.88 to 1.57. The upper end of that interval is the gene's LOEUF score, 1.57, which puts it in group 6 of 6, group 1 being the genes least tolerant of losing a copy. Missense variants: 352 observed, 354.16 expected, observed/expected ratio (o/e) 0.99, 90% interval 0.91 to 1.09. Synonymous variants: 122 observed, 128.05 expected, observed/expected ratio (o/e) 0.95, 90% interval 0.82 to 1.11.
Homologues: Orthologues: macaque SLC38A11 (98% identical), chimpanzee SLC38A11 (94% identical), pig SLC38A11 (88% identical), rabbit SLC38A11 (86% identical), dog SLC38A11 (85% identical), guinea pig SLC38A11 (81% identical), rat Slc38a11 (80% identical), mouse Slc38a11 (80% identical), zebrafish slc38a11 (57% identical), tropical clawed frog slc38a11 (56% identical), Drosophila melanogaster CG13743 (35% identical), Caenorhabditis elegans R02F2.8 (12% identical), and 5 more. Paralogues in human: SLC38A3 (24% identical), SLC38A4 (24% identical), SLC38A1 (24% identical), SLC38A2 (23% identical), SLC38A6 (23% identical), SLC38A5 (21% identical), SLC38A10 (19% identical), SLC38A7 (19% identical), SLC38A8 (18% identical), SLC38A9 (16% identical), SLC36A1 (16% identical), SLC36A3 (16% identical), and 3 more.
Diseases named in the same sentence as SLC38A11 in open-access papers:
SLC38A11 is named in the same sentence as 6 diseases in open-access papers, as found by Europe PMC text mining. Sharing a sentence is not in itself a finding about the gene and the disease. The quoted sentences say what the papers report.
mucinous adenocarcinoma (1 paper, 2024). An invasive adenocarcinoma composed of malignant glandular cells which contain intracytoplasmic mucin. "Significant results (P< 0.05) included associations with WNT11 and FBXL16 and body mass index (BMI), MSLN and mucinous adenocarcinoma, and SLC38A11 and metastasis." (PMID 38680862, 2024).
Obesity (1 paper, 2022). Accumulation of substantial excess body fat. "The mapped genes (FTO, SLC38A11, and RNA5SP111) of the identified PCOS SNPs in our study were also associated with obesity-related traits, including WHR, WHR adjusting for BMI, and childhood BMI (CBMI), suggesting the shared genetic architecture of PCOS, T2D, and obesity." (PMID 36105080, 2022).
tumor (3 papers, 2021 to 2025). "CCDC190 and SLC38A11 were only detected in single or small clusters of ES cells within the tumour, consistent with the hypothesis that these proteins are expressed by ES-CSCs and are, therefore, candidate therapeutic targets to eradicate ES-CSCs." (PMID 34403115, 2021). "Most ES expressed neurexin-1 (96%) and ELFN2 (96%), whereas SLC38A11 and CCDC190 were detected in just 41% and 67% of the tumours examined, respectively." (PMID 34403115, 2021).
cancer (1 paper, 2024). A tumor composed of atypical neoplastic, often pleomorphic cells that invade other tissues. "Of these, ALDOB, WNT11, MSLN, RAC3, and IL1RN have known roles in CRC, FBLX16 has known roles in other cancers, and SLC38A11 and WBSCR27 are relatively uncharacterized." (PMID 38680862, 2024).
SLC38A11 also shares sentences with these, for which no sentence is quoted: lymphoma (1 paper); melanoma (1).